OR56A5 (olfactory receptor family 56 subfamily A member 5)
Description:
Odorant receptor.
Synonyms: OR56A5P
Tractability: Antibody: UniProt places it where antibodies can reach, with medium confidence; UniProt predicts a signal peptide or a membrane-spanning region; its Gene Ontology location is reachable by antibodies, with medium confidence.
Gene: Protein-coding gene on chromosome 11 (5,967,553 to 5,968,494, reverse strand). Ensembl gene ENSG00000188691.
Subcellular location: Cell membrane
Pathways (Reactome):
Sensory Perception: Expression and translocation of olfactory receptors
Gene Ontology:
Molecular function: olfactory receptor activity; G protein-coupled receptor activity; signaling receptor activity
Biological process: cellular response to lipid; detection of chemical stimulus involved in sensory perception of smell; G protein-coupled receptor signaling pathway; system process
Cellular component: plasma membrane; membrane
Genetic constraint (gnomAD): Loss-of-function variants: 10 observed, 13.58 expected, observed/expected ratio (o/e) 0.74, 90% interval 0.45 to 1.25. The upper end of that interval is the gene's LOEUF score, 1.25, which puts it in group 5 of 6, group 1 being the genes least tolerant of losing a copy. Missense variants: 377 observed, 377.44 expected, observed/expected ratio (o/e) 1, 90% interval 0.92 to 1.09. Synonymous variants: 156 observed, 149.75 expected, observed/expected ratio (o/e) 1.04, 90% interval 0.91 to 1.19.
Homologues: Orthologues: guinea pig OR56A5 (83% identical), dog OR56A4B (81% identical), zebrafish adra1ab (18% identical), Caenorhabditis elegans ser-5 (17% identical), zebrafish adra2db (15% identical), zebrafish adra2da (15% identical). Paralogues in human: OR56A4 (87% identical), OR56A1 (79% identical), OR56A3 (72% identical), OR13F1 (31% identical), OR5T1 (29% identical), OR5T3 (28% identical), OR5T2 (26% identical), ADRA1A (18% identical), ADRA1B (18% identical), ADRB1 (17% identical), DRD2 (17% identical), ADRA2A (17% identical), and 6 more.
Diseases named in the same sentence as OR56A5 in open-access papers:
OR56A5 is named in the same sentence as 1 disease in open-access papers, as found by Europe PMC text mining. Sharing a sentence is not in itself a finding about the gene and the disease.
OR56A5 shares sentences with these, for which no sentence is quoted: retinitis pigmentosa (1 paper).